TPO (thyroid peroxidase)
Diseases named in the same sentence as TPO in open-access papers (continued):
Sharing a sentence is not in itself a finding about the gene and the disease.
tumor (continued). "Moreover, the size of the tumor and the concurrent calcification varied in different levels of the TPO antibody; however, this did not affect LNM." (PMID 40496557, 2025). "Furthermore, Xing M demonstrated that activation of MAPK signaling pathway resulted in upregulation of tumor-promoting genes (e.g. VEGFA, MET, HIF1A, UPA, UPAR, TGFB1, and TSP1) as well as downregulation of tumor suppression and thyroid genes (e.g. TIMP3, SLC5A8, DAPK1, NIS, TSHR, and TPO)." (PMID 35600399, 2022). "Therefore, although decreased, the expression of TSH-R, NIS, pendrin, TPO and TG is preserved, while the expression of Duox2 is not altered or is slightly increased, and these tumor cells can even synthesize TH." (PMID 33673669, 2021). "Of 2,972 TUs, DE analysis retrieved 127 of Class 1 TUs significantly up-regulated in tumor specimens (adjusted P-value below 0.01, DESeq), including multiple intergenic transcripts and transcripts antisense to protein-coding genes, such as HDAC9, TPO, and FBXL7." (PMID 31732695, 2019). "Analysis of TPO and TG expression levels, among tumors, according to the subtype of molecular alteration identified, conducted to the observation that the tumor sample presenting both the RET/PTC3 rearrangement and the p.A67G showed the lowest TPO expression level amongst all tumor samples." (PMID 22481925, 2012). "However, it is not known whether the TPO mRNA expression in the tumor changed compared to the expression in normal canine thyroid gland." (PMID 34209805, 2021). "There were significant differences in the longest diameter, tumour lesion site, LNM in the central region and lateral neck, and TSH, TG-Ab, TPO-Ab, and Tg levels between the no ETE and mETE groups (P < 0.05)." (PMID 37884592, 2023). "This study found that there were significant differences in the longest tumour diameter; lesion site; central and lateral LNM; and TSH, TG-Ab, TPO-Ab, and Tg levels between the no ETE and mETE groups (P < 0.05)." (PMID 37884592, 2023). "To mitigate this, we classified normal TFCs using 3 additional markers (i.e., TFF3, TPO, SLC26A4) that were previously shown to be expressed in normal thyroids but not in tumor cells." (PMID 37053016, 2023). "As in non-metastatic tumor thyroid tissue, the efficacy of radioiodine therapy will depend mainly on the presence of NIS to accumulate iodine and on the TPO/Duox2 system to oxidize radio-iodide into TG radioiodine." (PMID 33673669, 2021). "In DTC, an increase in ROS is observed, mainly as a result of Duox2 (not because the expression of Duox2 increases, but by decreasing the expression of TPO, the production of H2O2 generated by Duox2 is not consumed and accumulates in the tumor cell)." (PMID 33673669, 2021). "Finally, no significant changes were observed on the expression of genes related to thyroid cell differentiation (TG, TPO, SLC5A5 and TSHR) key players on the tumor progression and survival rates in PTC (data not shown)." (PMID 36776296, 2023).
cancer (48 papers, 2001 to 2026). A tumor composed of atypical neoplastic, often pleomorphic cells that invade other tissues. "The downregulation of TPO expression in lesion area of thyroid tissue and disruption of TPO mRNA maturation has been suggested to be associated with malignant neoplasm." (PMID 24745015, 2014). "Three thyroid-specific genes (TG, TPO, and NIS), six cancer-associated lncRNAs (MALAT1, NEAT1, HOTAIR, H19, PVT1, MEG3), and two housekeeping genes (GAPDH and P0) were analyzed using Droplet Digital PCR (ddPCR)." (PMID 33030666, 2021). "In conclusion, we found that the biochemical properties of the TPO protein expressed in cancer and normal breast tissue are similar to those observed for the thyroid TPO." (PMID 29513734, 2018). "The expression level of TPO in normal tissues was on average at least four times higher than in the matched cancer samples and this difference was statistically significant (P-value < 0.001)." (PMID 28575127, 2017). "We have demonstrated that TPO is present in both cancer and normal breast tissue, which confirms the results of Muller and collaborators." (PMID 28575127, 2017). "TPO expression was detected in both cancer cells and in the peri-tumoral ductal epithelium (considered as normal breast tissue)." (PMID 28575127, 2017). "TPO immunostaining was observed in normal and cancer breast tissue samples as well when pooled human serum with high levels of TPOAbs was used." (PMID 28575127, 2017). "We have shown that TPO transcripts were present in both normal and cancer tissue samples, although the amounts in the latter were reduced." (PMID 28575127, 2017). "First, we evaluated the TPO gene expression in matched cancer and normal tissue using RT-qPCR with a pair of primers (forward: exon 5/6, reverse: exon 6) amplifying all known TPO isoforms." (PMID 28575127, 2017). "The difference in TPO protein expression between normal tissue and cancer samples was borderline significant (P-value = 0.05)." (PMID 28575127, 2017). "A survival study was carried out, limited to patients with cancer, according to total TPO level and TNM stage." (PMID 26300979, 2015). "In malignant tumours, TPO synthesis is inhibited to varying degrees and maturation is deregulated resulting in overexpression of short splice variants." (PMID 18212751, 2008). "According to gene expression profiling analysis in thyroid cancer vs non-cancer tissue, TPO was one of the top 12 candidate markers in terms of diagnostic utility." (PMID 18212751, 2008). "Intermediate TPO immunostaining (20–70%) was observed in the remaining 37 carcinomas, that is, 16 PCs and 21 FCs." (PMID 18212751, 2008). "The findings suggest that TPO expression is significant and may play an important role in regulating cancer development." (PMID 37407700, 2023). "Therefore, TPO expression is commonly used clinically to identify the benign and malignant thyroid diseases." (PMID 37407700, 2023). "TPO-RA studies in cancer are mainly retrospective or phase 2 trials." (PMID 33799591, 2021). "Conversely, BRAFV600E knock-in mice (BRAF-Lox/TPO-Cre) generated PTC-like cancers." (PMID 31936153, 2020). "We also show that biochemical characteristics of the TPO protein expressed in normal (184A1) and cancerous cell lines (MCF-7 and MDA-MB-231), independently of the cancer differentiation status, resemble those of TPO present in immortalized normal thyrocytes (NTHY cells)." (PMID 29513734, 2018). "Varying TPO staining intensities were observed in cancer cells." (PMID 28575127, 2017). "Here we detected the positive TPO staining in all cancer and normal breast tissue samples." (PMID 28575127, 2017). "However, the long-term effect of TPO-RA on malignant tumors is still unknown, and thus, it should be used with caution." (PMID 30969381, 2019). "Accordingly, we hypothesized the patient’s cancer was the primary cause, but it cannot be ruled out that it was possibly a side effect of TPO-RA." (PMID 30969381, 2019).
cancer (continued). "Additionally, we observed that TPO levels are lower in more advanced cancers." (PMID 28575127, 2017). "Unexpectedly, the platelet count was increased by docetaxel which was consistent with the previous clinical study reporting that co-administration of docetaxel could spare platelet counts in cancer patients who received carboplatin by elevating circulation TPO concentration in blood." (PMID 28793897, 2017). "The lower expression of TPO in these two patients may increase the risk of their benign lesion developing into a carcinoma, if the thyroid gland is not removed." (PMID 24745015, 2014). "Functionally, IGF2BP2 promotes proliferation, suppresses thyroid differentiation genes (TSHR, SLC26A4, SLC5A5, TPO, PAX8, FOXE1, and NKX2.1), and enhances cancer stemness." (PMID 41522349, 2026). "We identified five genes (KCNJ16, SLC26A4, TG, TPO, and SYT1) as potential cancer treatment targets." (PMID 37208644, 2023). "In human carcinoma cells, PFOS and PFOA inhibited TPO activity, an enzyme important for TH biosynthesis." (PMID 36422892, 2022). "The remaining gene of the 9, thyroid peroxidase (TPO), has a less established role in cancer with a low cancer-literature-relevance score of 22.0, but it has been shown that autoantibodies to TPO predict BrCa risk." (PMID 34007962, 2021). "TPO biological activity is reduced and TPO immunostaining is weak or absent in most carcinomas when using the monoclonal antibody MoAb47." (PMID 34638232, 2021). "We have observed a decrease in TPO expression in cancer tissue samples compared to non-cancerous tissue in all but three patients." (PMID 28575127, 2017). "The negative TPO expression found in undifferentiated carcinomas, where cells lack their endocrine function, supports an association between cell differentiation and TPO levels." (PMID 26300979, 2015). "Diagnostic concordance between TPO-negative, NCB-based preliminary and postoperative final diagnosis was 100% for carcinomas of papillary (n = 17), widely invasive follicular (n = 1), medullary (n = 1) and undifferentiated (n = 3) subtypes." (PMID 18031322, 2008). "The TPO reaction was negative or low grade (⩽10%) in 52 out of the 91 carcinomas (41 PCs and 11 FCs) and positive (100%) in two PCs." (PMID 18212751, 2008). "Notably, TPO, DIO1, and SLC26A4 were consistently downregulated in both cancer subtypes." (PMID 40746809, 2025). "It is unclear whether TPO-RAs increase thrombosis in patients with cancer since no comparison group was included in most of the studies." (PMID 33799591, 2021). "It was suggested that the continued expression of TPO in cancer might predict clinical outcome, rather than the lack thereof." (PMID 26300979, 2015). "IFGBP4, TPO, BDNF, and FGF-7 demonstrated higher FF levels in adolescents without cancer compared to donors." (PMID 39211054, 2024). "Not surprisingly, similarity among different cancer types was identified in only 6 out of 23 clusters, including E3 (IRS2, KRT6A), E5 (CD24, STMN1), E8 (GKN1, MUC5AC), E9 (PHGR1, TFF3), E10 (TFF3, TPO) and E13 (VTN and ITIH5)." (PMID 36333338, 2022).
infection (19 papers, 2009 to 2025). The state of being infected such as from the introduction of a foreign agent such as serum, vaccine, antigenic substance or organism. "Prior infection with T. gondii was associated with an elevation of autoantibodies to thyroid peroxidase." (PMID 31533667, 2019). "With autoreactivity, intolerance, infection, and other underlying conditions shown to berelevant causes of csU, it is unlikely that IgE-anti-TPO is the relevant mast cellactivator in all csU patients." (PMID 21532759, 2011). "The potential association between eltrombopag and infection deserves further investigation, but probably patients treated with TPO-RA are those with more severe and longer cytopenias, being at higher risk of infections because of these circumstances, not because of TPO-RA treatment." (PMID 39274330, 2024). "Similar to our findings, anti-TPO increased 3 months after acute phase of infection." (PMID 40918680, 2025). "Subsequent epitope mapping and sequence alignment revealed that the main epitopes of TPO and NPC1, which display elevated autoantibody levels after infection, have a sequence similarity containing five identical residues." (PMID 39414823, 2024). "Therefore, TPO-RA offers an attractive alternative as a non-immunomodulatory agent, which can be used to spare glucocorticoid and immunosuppressant administration, thereby reducing the risk of infection." (PMID 38495431, 2024). "Laboratory investigations showed that total IgE levels (22 IU/mL) and tryptase (4.7 ng/mL) were within normal ranges, thyroid function was adequate, no anti-thyroid peroxidase (TPO) antibodies were detected, and there were no signs of infection with parasites or Helicobacter pylori." (PMID 36611183, 2023). "Some analytes were not significantly increased with infection but were significantly reduced by treatment with the anti-IL-7Rα M595: MCP-1, MCP-3, MDC, MIP-1α, MIP3β, GCP-2, IL-18, Tissue Factor, and TPO." (PMID 23057802, 2012).
immune diseases (9 papers, 2015 to 2023). "One patient with a history of auto-immune disorders experienced a relapse, which was overcome by 2nd line therapy with TPO-RA, leading to a stable CR eventually." (PMID 36195695, 2023). "Immune disorders lead to reactivity to thyroid autoantigens such as thyroid peroxidase (TPO), thyroglobulin (TG), and thyroid-stimulating hormone receptor." (PMID 36362236, 2022). "It is also important to highlight that in many auto immune diseases anti-TPO antibodies are elevated." (PMID 30288165, 2017). "Also one patient had anti-dsDNA, one had P-ANCA, and two had anti-TPO and anti-TG positivity, with normal thyroid function tests no auto-immune diseases." (PMID 25878633, 2015).
cardiovascular disease (8 papers, 2014 to 2025). "Therefore, clarifying the association between having a TPO-Ab titer in the normal range and yearly progression in CIMT (i.e., active arterial wall thickening) among euthyroid individuals could help inform strategies for preventing cardiovascular disease." (PMID 35159980, 2022).
endocrine disorder (7 papers, 2010 to 2023). "In the gene group of endocrine system disorder, the most important gene was thyroid peroxidase (TPO), this gene was overexpressed, and the next genes carbonic anhydrase VI (CA6), caveolin protein 1 (CAV1), and solute carrier family type 12 (SLLC12A3) were underexpressed." (PMID 35059043, 2022).
inflammation (3 papers, 2021 to 2026). Aberrant reaction of the microcirculation characterized by movement of fluid and leukocytes from the blood into extravascular tissues. "Chronic autoimmune inflammation in the thyroid gland leads not only to the formation of anti-TPO, anti-Tg, and anti-TSHR but also to the formation of antibodies against PLA2R, since it is expressed by thyroid glandular cells." (PMID 40076824, 2025).
metabolic disorders (3 papers, 2022 to 2024). "The metabolome of the control group clustered and showed a separation trend to that of the anti-TPO antibodies positivity group, indicating that metabolic disorders associated with anti-TPO antibodies positivity occurred." (PMID 35331172, 2022). "In summary, we performed 1H-NMR metabolomics on cord blood of a nested case–control cohort of 22 pregnant women to reveal the anti-TPO antibodies positivity associated fetal metabolic disorder." (PMID 35331172, 2022). "From comparison of the results of MESA and pathway analysis, we proposed that anti-TPO antibodies positivity was associated with metabolic disorders in amino acid metabolism, especially in phenylalanine metabolism." (PMID 35331172, 2022). "Further large-scale studies are recommended to further explore the roles of anti-TPO antibodies positivity associated cord blood metabolic disorder observed in this study." (PMID 35331172, 2022). "The fetal metabolic disorder associated with anti-TPO antibodies positivity may be affected by other clinical factors besides those included in the present study." (PMID 35331172, 2022). "Appropriate doses of medical treatment and dietary changes are thought to slow the inflammatory process, leading to a decrease in Anti-TPO and Anti-TG levels to levels lower than those at the initial diagnosis, improvement in thyroid function, and regression in metabolic disorders." (PMID 38892793, 2024). "The results of the present study suggested a correlation between anti-TPO antibodies positivity and fetal metabolic disorder, and called more attention to the clinical outcome of gestational anti-TPO antibodies positivity to both postpartum and the newborn health." (PMID 35331172, 2022).
hematologic diseases (2 papers, 2025). "Furthermore, the DMAG-induced ERK/HIF1/NF-E2 pathway is independently of the TPO signal, offering a novel strategy for drug screening in the treatment of hematologic diseases." (PMID 41296464, 2025).
genetic disorders (1 paper, 2012). "In addition, other genetic disorders may be more effective than TPO mutations in CH patients with dyshormonogenesis including the sodium symporter (NIS) gene, the pendrin gene (PDS), the thyroid oxidase gene 2 (THOX2 or DUOX2), and thyroglobulin gene." (PMID 22919382, 2012).
infectious disease (1 paper, 2019). A disorder directly resulting from the presence and activity of a microbial, viral, or parasitic agent in humans. "As a means of avoiding high costs, risks of infectious diseases, and platelet blood transfusion, TPO-RA can be used to restore the perioperative platelet level." (PMID 30969381, 2019).
movement disorder (1 paper, 2021). Neurological conditions resulting in abnormal voluntary or involuntary movement, which may impact the speed, fluency, quality and ease of movement. "Diagnosis should therefore be suspected in any patient with unexplained movement disorders, and anti-thyroglobulin (Tg) and anti-thyroid peroxidase (TPO) dosed in serum and CSF even when thyroid hormone levels are normal." (PMID 34925200, 2021).
TPO also shares sentences with these, for which no sentence is quoted: Abdominal obesity (6 papers); Addison’s disease (6); Turner syndrome (5); alopecia (4); autoimmune gastritis (4); connective tissue disease (4); dementia (4); myasthenia gravis (4); papillary carcinoma (4); parasitic infections (4); antiphospholipid syndrome (3); echinococcosis (3); epilepsy (3); Hyperglycemia (3); multiple sclerosis (3); neurological disease (3); pernicious anemia (3); acute kidney injury (2); Alzheimer disease (2); Arthritis (2); Atrophy (2); cataract (2); cerebral infarction (2); cognitive decline (2); cysticercosis (2); endothelial dysfunction (2); gastric cancer (2); heart failure (2); hepatocellular carcinoma (2); Hypocalcemia (2).
A further 160 diseases each share a sentence with TPO in 2 papers or fewer.